APP (amyloid beta precursor protein)
Diseases named in the same sentence as APP in open-access papers (continued):
Sharing a sentence is not in itself a finding about the gene and the disease.
breast cancer (continued). "The remaining two studies reported that androgens upregulated APP expression in both prostate and breast cancer cells." (PMID 41614805, 2025). "Analysis of the correlation between CD74 and APP and breast cancer patient survival in the TCGA cohort revealed that higher CD74 levels were associated with significantly longer survival times." (PMID 40357856, 2025). "Two studies identified APP as an androgen-responsive gene, showing that androgens upregulated APP expression in prostate and breast cancer cells and promoted the proliferation of cancer cells." (PMID 41614805, 2025). "Our data suggest that the results are robust in different NSCLC datasets and the key target genes identified (ITGA2B, FLNA, GRB2, FCGR2A, and APP, etc.)seem to also be strongly expressed in the breast cancer and pancreatic cancer datasets we analyzed." (PMID 41226816, 2025). "APP is an androgen-induced gene that promotes the proliferative activity of breast cancer cells and has been recognized as a potent prognostic factor in patients with ER-positive breast cancer." (PMID 39910672, 2025). "Amyloid precursor protein (APP), for example, is upregulated in advanced breast cancer and has been associated with increased cancer cell proliferation, migration, and invasion." (PMID 41233352, 2025). "APP has been reported to be upregulated in breast cancer, glioblastoma, nasopharyngeal carcinoma, pancreatic cancer, colon cancer, prostate cancer, and HCC." (PMID 39332525, 2024). "Inhibiting APP expression or its processing products, such as soluble amyloid precursor protein alpha (sAPPα), can reduce breast cancer cell migration and proliferation." (PMID 39123408, 2024). "For instance, in breast cancer, APP has been shown to promote cell migration and invasion by activating the mitogen‐activated protein kinase (MAPK) signalling pathway, which is crucial for epithelial‐mesenchymal transition (EMT) and metastasis." (PMID 38445803, 2024). "In breast cancer samples, ATP7A (18%), amyloid beta precursor protein (APP) (11%) and ATP7B (9%) were the more frequently mutated genes." (PMID 37180167, 2023). "Overexpression of APP was found to increase markers of the EMT in breast cancer cells, while silencing of APP had the opposite effect." (PMID 36768435, 2023). "The secreted form of APP is also called protease nexin-2, and is cleaved by γ-secretase, which is also being studied as a potential therapeutic target against breast cancers, including TNBC." (PMID 36768435, 2023). "While APP buildup has been reported previously in breast cancer tumors and the corresponding metastatic lymph nodes, the presence of its β‐secretase cleavage product, Aβ, was not reported." (PMID 34592066, 2022). "Knockdown of APP led to reduced breast cancer cell motility and growth, in part, by induction of caspase-3-mediated apoptosis." (PMID 36142659, 2022). "Initially, it was found that the proteolytic cleavage of APP by the α‐secretase (non‐amyloid) pathway reduces proliferation and migration in breast cancer." (PMID 34592066, 2022). "It was found that APP overexpression increased the migratory and invasive ability of human breast cancer cells, whereas APP silencing significantly inhibited cell migration and invasion." (PMID 34592066, 2022). "In breast cancer, APP has been shown to mediate cell proliferation and motility through the AKT signaling pathway." (PMID 35678671, 2022). "A recent study revealed that APP can promote the aggression of breast cancer cells by activating the MAPK signaling and is upregulated in lung cancer." (PMID 36157221, 2022). "Later, it was confirmed that APP controls breast cancer through the mitogen‐activated protein kinases (MAPK) signaling pathway, regulating different kinases and the expression of filaments such as cadherins, cytokeratins, and vimentin." (PMID 34592066, 2022).
breast cancer (continued). "These authors also discovered that if the proteolytic cleavage of APP is processed by α‐secretase (the non‐amyloid pathway), proliferation and migration in breast cancer are reduced." (PMID 34592066, 2022). "Generally, it was shown that APP overexpression increases the migratory and invasive ability of human breast cancer cells, whereas APP silencing significantly inhibits cell migration and invasion." (PMID 34592066, 2022). "Survival analysis found APP, TRIM25 and ELAVL1 to have significant associations with overall survival (log-rank p-value <0.05) in breast cancer." (PMID 34193143, 2021). "Neratinib, used to treat HER2+ breast cancer, reduced chaperone levels and expression of Tau and APP via macroautophagy, and neratinib interacted with AR12 to cause further reductions in protein levels." (PMID 34252884, 2021). "In the literature, APP is a well-established cancer biomarker, a target of ADAM10, and has been strongly linked with breast cancer growth, metastasis and migration." (PMID 34193143, 2021). "Regarding APP, current studies have demonstrated its overexpression and characteristic of oncogenes in some malignancies such as breast cancer, pancreatic cancer, and NSCLC." (PMID 32328125, 2020). "The expansion of importance in breast cancer emphasizes the examination of ADAM10 cleavage of APP in other cancers." (PMID 32265938, 2020). "In contrast with several above-mentioned MPs (e.g., CD44, EGFR/ERBB2, and APP) that have been well studied, the interacting partners and pathways associated with CHRNA9 in breast cancer remain to be elucidated." (PMID 31311925, 2019). "It was reported that the expression of APP is increased in both malignant breast cancer cell lines and breast cancer tissues." (PMID 31998645, 2019). "This, on one hand, implicates that the network, once trimed to capture breast cancer heterogeneity, is shifted towards ER-driven and, on the other hand, suggests the critical roles played by APP in mediating carcinogenesis and subtype differentiation." (PMID 28754978, 2017). "The APP-knockdown breast cancer cells also showed decreased tumor growth in both a 3D in vitro cell culture and in an in vivo mouse model." (PMID 26840089, 2016). "In breast cancer, it has been recently shown that APP promotes cell proliferation and favors breast cancer cells motility." (PMID 26673618, 2016). "APP expression is increased in breast cancer cell lines that exhibit greater metastatic tendencies, such as motility and proliferation." (PMID 26840089, 2016). "When APP in a variety of breast cancer cell lines with increasing metastatic potential was knocked down, the cell lines had reduced cell growth and underwent G1 arrest due to induction of the cell cycle inhibitor p27kip1." (PMID 26840089, 2016). "In order to investigate the correlation between APP expression and malignancy of breast cancer, the expression level of APP was examined in a series of human and mouse breast cancers with increasing malignancy." (PMID 25491510, 2014). "These 3D culture and in vivo xenograft studies strongly support the role of APP in the promotion of breast cancer cell growth." (PMID 25491510, 2014). "The APP expression is important to regulate cell growth, apoptosis, and motility of breast cancer, possibly through engagement of AKT-mediated signaling pathways." (PMID 25491510, 2014). "Second, the inhibition of APP expression in breast cancer cells effectively prevents cell growth and motility in vitro and in vivo models." (PMID 25491510, 2014). "We found that the expression of APP is increased in mouse and human breast cancer cell lines, especially in the cell line possessing higher metastatic potential." (PMID 25491510, 2014). "We investigated the pathophysiological function of APP by knocking it down using the shRNA targeting APP in MDA-MB-231 malignant human breast cancer cells." (PMID 25491510, 2014).
breast cancer (continued). "In summary, we found that the expression of APP is increased both in mouse and human malignant breast cancer cell lines and similarly in human breast cancer tissues." (PMID 25491510, 2014). "In this study, we studied the pathological role of APP in breast cancer and revealed its potential mechanism." (PMID 25491510, 2014). "First, we demonstrated increased expression APP in breast cancer cells and its correlation with malignancy." (PMID 25491510, 2014). "The expression level of APP in multiple breast cancer cell lines was measured by Western blot analysis and the breast cancer tissue microarray was utilized to analyze the expression pattern of APP in human patient specimens." (PMID 25491510, 2014). "Next, we examined IGF-1/AKT signaling pathway in APP-kd cells since AKT/FOXO signaling axis have been identified as critical signaling intermediates for breast cancer survival, growth, and migration as well as therapeutic drug resistance." (PMID 25491510, 2014). "Third, we also demonstrated that APP is mechanistically linked to the AKT/FOXO and AKT/GSK3-β pathways which are known to modulate cell growth, survival, and invasion of breast cancer cells through the regulation of target genes including p27kip1 and survivin." (PMID 25491510, 2014). "Since the reduced p27kip1 expression is correlated with tumor aggressiveness and poor patient survival, this finding suggests that APP plays a significant role in regulation of p27kip1 in a malignant human breast cancer." (PMID 25491510, 2014). "APP knockdown (APP-kd) in breast cancer cells reduced cell growth via p27kip1 induction, promoting apoptosis, increasing sensitivity to therapeutic treatments, and delayed cell migration and invasion ability upon stimulation." (PMID 25491510, 2014). "In this study, we explored the pathological role of APP in malignancy of breast cancer and its potential molecular mechanism related with cell proliferation and metastasis." (PMID 25491510, 2014). "In order to solidify the finding of APP functions on cell growth, we employed three-dimensional (3D) cultures of breast cancer cells in reconstituted basement membrane (Matrigel, BD Bioscience)." (PMID 25491510, 2014). "While those results are not overlapped with the phenotype of our APP knockdown experiments, both reports strongly suggest the pathological role of APP in breast cancer pathogenesis." (PMID 25491510, 2014). "This positive correlation between APP expression and malignancy was further confirmed in mouse breast cancer cells; 67NR, 4T07, and 4T1 cells which are derived from the same primary tumor." (PMID 25491510, 2014). "Another study suggests that the cleavage peptide, sAPPα, could be the main factor that promotes breast cancer progression mediated by APP." (PMID 41614805, 2025). "This increase in APP mRNA in response to DHT was also observed in breast cancer cells." (PMID 41614805, 2025). "Two studies explored the impact of androgens on APP expression in prostate and breast cancers." (PMID 41614805, 2025). "Recently, the role of APP in promoting the migration and invasion of breast cancer cells through regulating the MAPK signaling pathway has also been suggested, which may be related to our PPI network results." (PMID 39332525, 2024). "The pathological role of APP in malignancy, particularly in its potential molecular mechanisms related to cell proliferation and metastasis, has been explored in breast cancer, suggesting a similar exploration in RCC could yield valuable insights." (PMID 38445803, 2024). "In breast cancer, it has been discovered that APP promotes tumor growth and metastasis." (PMID 39123408, 2024). "Moreover, according to the literature, APP has shown differential expression in different breast cancer cell lines." (PMID 34592066, 2022). "APP was also shown to induce migration in breast cancer cells, especially in the presence of IGF-1." (PMID 26840089, 2016).
breast cancer (continued). "Moreover, the analysis of human breast cancer tissues revealed a significant correlation between the level of APP and tumor development." (PMID 25491510, 2014). "Notably, knock-down of APP in metastatic breast cancer cells limited cell migration and invasion ability upon stimulation of IGF-1." (PMID 25491510, 2014). "Our data strongly indicate the pathological role of APP in breast cancer." (PMID 25491510, 2014). "The present data strongly suggest that the increase of APP expression is causally linked to tumorigenicity as well as invasion of aggressive breast cancer and, therefore, the targeting of APP may be an effective therapy for breast cancer." (PMID 25491510, 2014). "Furthermore, research has demonstrated APP’s involvement in driving tumor growth and invasion in breast cancer, providing reason that APP may exert similar pro-tumorigenic effects in GBM." (PMID 41003874, 2025). "It is involved in the cleavage and degradation of proteins on the cell membrane, mainly involving the degradation of two types of substrates, APP and Notch receptors, and plays an important role in the progression of breast cancer (BC) and AD." (PMID 39634655, 2024). "In addition, APP cleavage by ADAM10 was shown to have an oncogenic role in breast cancer." (PMID 36142659, 2022). "Likewise, knockdown of APP expression reduced breast cancer cell migration and cell growth." (PMID 34066808, 2021). "Their results suggest that APP might suppress aggressiveness of breast cancer cells." (PMID 25491510, 2014). "Our findings that APP is functionally linked with AKT activation and GSK-3β/β-catenin pathways warrant the future study that elevated APP in malignant breast cancers is associated with dissemination of breast cancer into other target organs by promoting EMT process." (PMID 25491510, 2014). "Similarly, in addition to the result of MCF-10A cells, APP knockdown in MDA-MB-231 promotes sensitivity to therapeutic treatments of TRAIL or 5-FU, implying that targeting APP in malignant breast cancers may promote the sensitivity to therapeutic drugs." (PMID 25491510, 2014). "ER-positive breast cancer cells, MCF7s, treated with 10 nM DHT for 72 h, significantly increased APP mRNA levels (p < 0.01)." (PMID 41614805, 2025). "Silencing APP for 1, 2, and 4 days in both MCF7 and MDA-MB-231 breast cancer cells led to a significant decrease in cell proliferation." (PMID 41614805, 2025). "Genes such as APP, CDK1, CDK2, and ESR1 were the most frequently observed in this list and have been previously extensively characterized in breast cancer." (PMID 38378612, 2024). "In human breast cancer samples and tumor cell lines, JNK3, but not the other JNK isoforms, responded to amyloid precursor protein (APP) signaling, and subsequent JNK3 phosphorylation facilitated epithelial–mesenchymal transition of breast cancer cells." (PMID 37375361, 2023). "Co-expression of APP and ADAM10 was found to correlate with unfavorable prognosis and worse survival outcomes for patients with different subtypes of breast cancers." (PMID 36142659, 2022). "The present study identified four genes (AP2B1, APP, GPNMB and DLST) that were significantly downregulated by luteolin in breast cancer cell lines." (PMID 35678671, 2022). "The data suggested that the four genes, AP2B1, APP, GPNMB and DLST, were highly expressed in breast cancer and that AP2B1 was a suitable prognostic marker for breast cancer." (PMID 35678671, 2022). "AR12 and the breast cancer drug neratinib (NER) rapidly reduced expression of Tau, amyloid precursor protein (APP), superoxide dismutase 1 (SOD1) and TAR DNA-binding protein 43 (TDP-43)." (PMID 36227739, 2022). "The human protein atlas database also found that AP2B1, APP, GPNMB and DLST were highly expressed in breast cancer and that AP2B1 (cut-off value, 75%) was significantly associated with survival rate (p = 0.044)." (PMID 35678671, 2022).
breast cancer (continued). "As for the protective factors (IL1RL1, TXNIP, and APP), IL1RL1 was similarly identified to function as a tumor suppressor in mammary tumor." (PMID 32328125, 2020). "As an RNA‐binding protein, TARBP2 enhances invasion and metastatic colonization by directly binding APP and ZNF395 transcripts, thereby post‐transcriptionally enhancing their decay rate in breast cancer." (PMID 30657254, 2019). "In order to examine the clinical relevance of APP expression in breast cancer, a tissue microarray (TMA) containing various grades of breast cancer tissues and normal breast tissues was analyzed with an anti-APP antibody (22C11)." (PMID 25491510, 2014). "Our data also suggest that APP is involved in IGF-1/AKT signaling pathways, which are key regulatory pathways for cell growth and survival of breast cancer." (PMID 25491510, 2014). "Notch and APP are probably the best-studied γ-secretase substrates, and we have shown that GSI1 treatment downregulates the Notch pathway in breast cancer cells." (PMID 19513078, 2009). "Furthermore, we reported that Fe65, a binding protein of amyloid precursor protein (APP), was translocated into the nucleus by phosphorylation of APP and was involved in promoting cancer cell progressions in breast cancer." (PMID 37435453, 2022). "It was also discovered that APP has differential expression in different breast cancer cell lines, with triple‐negative breast cancer cell lines having the highest level of APP expression." (PMID 34592066, 2022). "Proteolytic cleavage of APP by the α-secretase pathway mediates proliferation and migration in breast cancer, while other pathways were not studied." (PMID 31137462, 2019). "Thus, our results strongly suggest that APP-mediated regulation of AKT/FOXO and AKT/GSK3β pathways are playing a significant role for breast cancer development." (PMID 25491510, 2014). "In addition, knockdown of APP in breast cancers augmented apoptotic markers and it is likely that advanced breast cancers (M-II, M-III, and M-IV) with knockdown of APP are more prone to enter into apoptosis." (PMID 25491510, 2014). "For instance, the APP (amyloid-beta precursor protein), ESR1 (estrogen receptor 1), TUBB (beta tubulin), and CUL3 (culin-3) genes have established links to promoting cancer cell survival, adhesion, differentiation, migration, and resistance to therapy in breast cancer." (PMID 38378612, 2024). "In addition, the HPA database demonstrated that AP2B1, APP, GPNMB and DLST were highly expressed in breast cancer; the increased expression of AP2B1 (cut-off value, 75%) was significantly associated with the survival rate (p = 0.044) of 1075 patients with breast cancer." (PMID 35678671, 2022). "In our study, we chose specific antibodies against Aβ peptides with low reactivity for its precursor APP to see whether Aβ immunoreactivity is present in xenograft tumors induced by triple‐negative inflammatory breast cancer cells." (PMID 34592066, 2022). "While it is known that APP is present in IBC, we found no published evidence on whether APP is cleaved to form Aβ peptides and aggregated Aβ amyloid in breast cancer." (PMID 34592066, 2022). "In this study, APP expression was highly expressed in non-luminal breast cancer, which demonstrated human epidermal growth factor receptor 2–overexpressed (HER2-OE, 39.3%) and triple-negative breast cancer (TNBC, 38.2%), as compared with 8% in luminal A cancer." (PMID 34066808, 2021). "However, the function of APP in the pathogenesis of breast cancer has not previously been determined." (PMID 25491510, 2014). "Moreover, M-III and M-IV showed such apoptotic markers to a much greater extent, suggesting that the cell survival of advanced breast cancer cells is more dependent on APP expression than non-malignant breast epithelial cells (M-I)." (PMID 25491510, 2014). "We found no published evidence on whether APP is cleaved to form Aβ peptides in breast cancer." (PMID 34592066, 2022).